IL6 (interleukin 6)
Diseases named in the same sentence as IL6 in open-access papers (continued):
Sharing a sentence is not in itself a finding about the gene and the disease.
COVID-19 (continued). "This dysregulation may lead to increased expression of IL-6 protein, which has implications for the inflammatory response associated with COVID-19." (PMID 37568870, 2023). "Furthermore, this synergistic combination of acetate and ALA significantly increased the expression of host interferon-β (IFN-β) and decreased the expression of host interleukins IL-1β and IL-6, which are associated with severe COVID-19." (PMID 37515117, 2023). "Association between IL-6 of patients with COVID-19 and variables." (PMID 37960722, 2023). "Of interest, numerous investigations have demonstrated that both moderate and severe COVID-19 instances may cause a hyperinflammatory reaction with increased levels of many cytokines such as IL-6, TNF-α, etc.." (PMID 37762499, 2023). "In this regard, many clinical conditions and biomarkers such as age, hypertension, Interleukin-6 (IL-6) or D-dimer are associated with COVID-19 severity but the prediction of the clinical course and the pre-existing conditions that confer increased risk, remain a challenge for physicians." (PMID 37809329, 2023). "IL-6 is a critical cytokine in COVID-19 associated with CRS." (PMID 37969879, 2023). "Based on this, we consider the possibility that IL-6 elevation with the presence of GGO in the early phase of COVID-19 might also associate with the development of long COVID-19." (PMID 37376606, 2023). "Other studies have demonstrated that persistently elevated serum IL-6 levels during COVID-19 are independently associated with in-hospital mortality, and rises of serum IL-6, IL-8 and TNF-α are probably age-dependent, translating to poorer outcomes among the elderly." (PMID 37568402, 2023). "Therefore, IL-6 serum level is augmented in hypogonadism patients that increase their susceptibility for COVID-19 severity." (PMID 37045862, 2023). "In this study, we found a significant association between COVID-19 severity and IL-6 levels." (PMID 37568161, 2023). "Growing evidence suggests that some SNPs can influence the susceptibility and severity of COVID-19. confirmed the role of the IL-6 cytokine and the genetic predisposition of the IL6 gene variant in response to infection as predictors of the severity of COVID-19 and adverse outcomes." (PMID 37390087, 2023). "The cytokine storm associated with severe COVID-19 is characterized by high levels of proinflammatory cytokines, including interleukin-1β (IL-1β), IL-2, IL-6, tumor necrosis factor (TNF), C-X-C motif chemokine ligand 10 or granulocyte-macrophage colony-stimulating factor (GM-CSF), among others." (PMID 37253946, 2023). "In this study, we demonstrated that increased IL-6 is associated with long COVID-19, as serum levels of IL-6 were found to be significantly elevated in patients after COVID-19 infection, whether in the acute or long COVID-19 phase." (PMID 37095536, 2023). "Furthermore, HE4 levels were compared and correlated with IL-6 and ferritin, which are closely associated with the analytical parameters heavily modulated by COVID-19." (PMID 37297598, 2023). "Thus, genotyping of cytokine-related polymorphisms, such as IL-6, in the context of COVID-19 has also been conducted, although the association between IL-6 polymorphisms and SARS-CoV-2 pathogenesis and severity has not been firmly established." (PMID 38138102, 2023). "Excessive IL-6 synthesis is implicated in several disease pathologies including COVID-19." (PMID 37761018, 2023). "It’s also suggested that Enterococcus may increase the production of pro-inflammatory cytokines such as TNF-alpha and IL-6, which have been shown to be elevated in patients with COVID-19 and are associated with severe disease." (PMID 36844398, 2023). "Similarly, IL-6 levels are significantly elevated and associated with adverse clinical outcomes of COVID-19." (PMID 37686837, 2023).
COVID-19 (continued). "Interestingly, IL-6 and IL-1β have both been implicated in the dysregulation (altering the normal levels) of DMETs, and their presence in COVID-19 pathophysiology warrants a similar investigation." (PMID 37180730, 2023). "Notably olfactory loss, and many neuropsychiatric disorders are associated with high levels of interleukin-6 (IL-6), an inflammatory marker which is also implicated in the cytokine storm in COVID-19 patients." (PMID 37599993, 2023). "Hair loss in COVID-19 may be associated with the action of proinflammatory cytokines, such as interleukin 1β, interleukin 6, tumor necrosis factor α, and interferon-γ." (PMID 36674238, 2023). "IL-6 has been identified to be associated with several infections, including COVID-19." (PMID 37095536, 2023). "Interestingly, multiple pathways, such as Interleukin-1 (IL-1), type 1 interferon, and IL-6 signaling pathways, which are associated with COVID-19 pathology, were highlighted." (PMID 37907741, 2023). "IL-6 and IL-18 may each contribute various aspects of these COVID-19-linked perturbations, according to a screen for potential agents." (PMID 36992283, 2023). "Previous studies had found the IL-6 rapid diagnostic system to be well-suited for various clinical applications, including early diagnosis of respiratory failure risk in COVID-19 patients, differentiation of influenza severity in children, and early detection of acute wound infection." (PMID 37214473, 2023). "Interleukin-6 levels are linked to the severity of COVID-19." (PMID 36833140, 2023). "We can conclude that the monitoring of the IL-6 level could be a therapeutic target in the treatment of the cause of inflammation in post-COVID-19 patients." (PMID 37373960, 2023). "IL-6 levels are markedly increased and linked to poor clinical outcomes in COVID-19 patients." (PMID 37504277, 2023). "In addition to regulating ER-associated genes, XBP1 binds directly to promoters for cytokines including interleukin 6 (IL-6), which is strongly induced in severe COVID-19 and associated with the risk of respiratory failure and death (60, -, 62)." (PMID 37306512, 2023). "In addition, our data serve as a basic determinant for long COVID-19 in association with high levels of the immune mediator IL-6." (PMID 37095536, 2023). "In addition, a meta-analysis evaluating 27 trials has confirmed the effectiveness of tocilizumab, where use of this anti-IL-6 antibody decreased 28-day all-cause mortality in patients hospitalized for COVID-19." (PMID 36941580, 2023). "Age, IL6 and length of hospital stay may be factors influencing myocardial injury caused by COVID-19." (PMID 37564653, 2023). "COVID-19 vaccine-associated myocarditis is believed to be primarily caused by uncontrolled cytokine-mediated inflammation with possible genetic components in the interleukin-6 signaling pathway." (PMID 36851240, 2023). "Thus, tocilizumab, a monoclonal IL-6R antibody that blocks the IL-6 signaling pathway and potentially reduces the risk of CS, was a recommended therapy for COVID-19." (PMID 37234160, 2023). "Low blood levels of plasmin and its precursor plasminogen correlate with a high risk for mortality and are associated with IL-6 upregulation in COVID-19 patients, reflecting its potential contribution to profibrogenic uPA accumulation and low-level fibrinolysis." (PMID 36674896, 2023). "Findings suggest that Long COVID-19 is associated with a range of sustained hematological alterations, including alterations in red blood cells, anemia, lymphopenia, and elevated levels of inflammatory markers such as ferritin, D-dimer, and IL-6." (PMID 37565145, 2023). "The authors concluded that elevated IL-6 levels may serve as an independent risk factor for severity and mortality in patients with COVID-19." (PMID 36982611, 2023). "Vaccination increased the hyperinflammatory response linked to IL-6 in the COVID-19 patients." (PMID 37896963, 2023).
COVID-19 (continued). "Therefore, it would be crucial to assess not only the protective effect of IL-6 inhibitors on inflammation caused by COVID-19 but also their therapeutic implications in cancer therapy." (PMID 37753372, 2023). "We also identified a pro-inflammatory cytokine profile associated with COVID-19, highlighting the IL-6 and IL-1β, which may work as potential biomarkers or predictors of long-COVID-19 when used alone or in combination with IFN-γ." (PMID 37018291, 2023). "Patients with high IL-6 levels have 29 times the risk of suffering from severe COVID-19." (PMID 38099004, 2023). "Moreover, IL-6 was significantly and independently associated with the degree of pulmonary infiltrates in COVID-19 and was able to detect infiltrate above median in respiratory infections other than SARS-CoV-2." (PMID 37733154, 2023). "Notably, our observations unveiled the presence of a range of genes linked to inflammation and COVID-19, such as IL-6, basigin, and MMP9." (PMID 37764186, 2023). "This RCT has shown that the administration of potassium canrenoate to patients with COVID-19-induced pneumonia may be associated with significant changes in certain inflammatory markers (interleukin-6, CD3%, TNF-α), potentially related to pulmonary fibrosis." (PMID 37762549, 2023). "Dysregulated immune responses are developed in Coronavirus disease-2019 (COVID-19) and Interleukin-6 (IL-6) levels are reflecting the severity of the clinical presentation." (PMID 37889917, 2023). "The tumor necrosis factor (TNF-α), IL-6, and IL-10 concentrations are the most important mediators of cytokine storm formation, and their levels clearly distinguish mild from severe cases of COVID-19 and are associated with poor prognosis of the disease." (PMID 37759873, 2023). "Therefore, IL-6 inhibitors have been used in patients with severe COVID-19, although they can increase the risk of developing pulmonary aspergillosis." (PMID 38205484, 2023). "The inflammatory load related to the COVID-19 pathophysiology is interleukin 6 (IL-6), whose high levels cause cardiovascular damage and the deterioration of the clinical condition of patients, especially of those who already have pre-existing comorbidities, such as chronic NCDs." (PMID 37415703, 2023). "Among the cytokines detected, IL-6 was significantly also increased in the peripheral blood of COVID-19 patients (p < 0.05), suggesting that IL-6 may associate with encephalitis." (PMID 36609561, 2023). "Intriguingly, severe COVID-19 patients display massive inflammation, possibly resulting from the loss of homeostatic robustness, which is clinically mitigated by the treatment with monoclonal antibodies against IL-6 (e.g., tocilizumab) and/or corticosteroids." (PMID 37063865, 2023). "Hence, the present study aims to evaluate the role of polymorphisms at IL6, IL6R, and IL6ST in COVID-19 severity aspects, along with their influence on IL-6 plasma levels during active COVID-19." (PMID 37243282, 2023). "IL-6 is one of the key factors in the cytokine storm caused by COVID-19." (PMID 36869206, 2023). "However, HFnorm was significantly higher in died COVID-19 patients, and the increase of this parameter was associated with a worse prognosis, higher mortality, and higher IL-6 levels." (PMID 36673664, 2023). "The data that advocate a beneficial role of ACEI and ARAII are based on the existence of lower levels of cytokines, decreasing inflammatory levels and IL6 expression in patients with severe COVID-19, and lower associated mortality data, as well as a possible protective factors for severe cases." (PMID 37512012, 2023). "Indeed, high serum levels of IL-6 were associated with poor clinical outcomes in severely ill COVID-19 patients." (PMID 37313412, 2023). "Therefore, in this study, we evaluated the association between the severity of periodontitis, COVID-19, IL-6, and CRP." (PMID 37568161, 2023).
COVID-19 (continued). "Furthermore, interleukin-6 (IL-6) is an important inflammatory cytokine mediator linked to the severity of COVID-19 symptoms." (PMID 37894169, 2023). "TNF-α and IL-6-mediated CRS causes significant acute respiratory distress in COVID-19 patients." (PMID 36817449, 2023). "Interestingly, PACVS-associated upregulation of IL-6 is correlated to an even more pronounced upregulation of IL-8, which has also been observed in post-COVID-19 ME/CFS." (PMID 38005974, 2023). "Particularly, an increased susceptibility for Candida infections in critically ill COVID-19 patients was suggested by the observation of impaired immune response to those pathogens characterized by the abrogated release of IL-6, TNF, IL-1α, and IL-1β toward Candida albicans." (PMID 36675940, 2023). "High plasma levels of IL-6 are strongly associated with lower survival in COVID-19 patients." (PMID 36674896, 2023). "Moreover, the proinflammatory cytokine IL-6 has been associated with increased EBV reactivation in COVID-19 patients, as significant levels of EBV viremia were found in 78% of critically ill COVID-19 patients compared to only 44.4% in non-COVID-19 patients." (PMID 37685871, 2023). "Inflammation is a key feature of COVID-19 and severe disease is associated with sudden release of pro-inflammatory cytokines such as IL-1, IL-6, TNF-α and interferon, called ‘cytokine storm’, leading to the migration of immune cells into the infection site, capillary damage, and multi-organ failure." (PMID 37817137, 2023). "We demonstrated that increased IL-6 is associated with long COVID-19." (PMID 37095536, 2023). "This could be because increased levels of interleukin-6, which have previously been associated with muscle atrophy and decline in COVID-19 patients, are associated with atrophy and reduced muscle function." (PMID 38001401, 2023). "Thus, the results of a retrospective, multicenter study confirmed that elevated systemic concentrations of pro-inflammatory bioregulators, including ferritin and IL-6, were associated with a more severe course of COVID-19 and multiple organ damage." (PMID 36766583, 2023). "COVID-19 severity was associated with higher levels of salivary and serum interleukin-6 levels." (PMID 37568161, 2023). "Furthermore, COVID-19 caused excessive production of proinflammatory cytokines such as IL-6, IL-2, IL-7, granulocyte-colony stimulating factor (G-CSF), Macrophage Inflammatory Protein-1 Alpha ((MIP-1-α)/CCL3, and TNF-α), termed as cytokine storm." (PMID 37377785, 2023). "Explore whether plasma IL-6 levels are similar across biomarker platforms and association with COVID-19 clinical outcomes." (PMID 37650680, 2023). "In COVID-19, IL-6, CRP, and LPS levels are elevated and associated with adverse clinical outcomes." (PMID 37238973, 2023). "Thus, hyperinflammation caused by CRS in COVID-19 patients with liver injury can be reversed by targeting IL-6 signaling." (PMID 36671484, 2023). "Additionally, this study examines and demonstrates the relationships between AD and COVID-19 with inflammatory signals such as interleukin 6 (IL-6), interleukin 1 (IL-1), and cytoskeleton-associated protein 4 (CKAP4)." (PMID 38259635, 2023). "The discovery of elevated levels of cytokines, like IL-6, in severe COVID-19 patients could be both a result and a cause of viremia, creating a potentially hazardous cycle that perpetuates itself." (PMID 38094124, 2023). "This analysis revealed that persisting inflammatory parameters, such as CRP, IL-6, d-dimer and ferritin as well as acute COVID-19 severity predicted the risk for persistence of structural lung abnormalities at follow-up, whereas dyslipidemia and dysglycemia did not." (PMID 36788324, 2023). "Notably, within this pathway, we observed the presence of several genes associated with inflammation and COVID-19 that have been previously identified by other researchers, including IL-6, basigin, and MMP9." (PMID 37764186, 2023).
COVID-19 (continued). "Interleukin-6 (IL-6) and oxygenation index (PaO2/FiO2) were missing in over 97% of hospitalizations and C-reactive protein and ferritin over 98% of the time; despite all four being identified as risk factors for COVID-19 related mortality." (PMID 36800930, 2023). "In addition, individuals with COVID-19 receiving treatment in intensive care units have been reported to have a higher risk of death when their IL-6 levels are elevated." (PMID 37240319, 2023). "Among them, the surplus levels of IFN-γ, TNF-α, IL-1, and IL-6 have been known to be associated with the dysfunction of the blood–brain barrier (BBB) as a part of priming the neuroinflammatory process in the human brain during COVID-19." (PMID 36672177, 2023). "When we performed a non-adjusted logistic regression analysis among patients with COVID-19, we discovered that 5 out of 13 predictor variables were significantly associated with IL-6 levels, including ICU admission, CRP, troponin, and severity index (P value < .05)." (PMID 37960722, 2023). "This may account for some of the differences in efficacy and leaves the question of infection risk largely unanswered for cases of COVID-19 treated with a combination of corticosteroid and IL-6 blockade." (PMID 37629609, 2023). "Importantly, increased levels of TNF-α and IL-6 are associated with the severity of disease in COVID-19 patients." (PMID 36864506, 2023). "While immunosuppressants can reduce cytokine storms triggered by TNF, IL-1, IL-6, and interferon, which may mitigate serious organ damage in COVID-19 patients, they also increase the risk of infections due to a reduced autoimmune response." (PMID 37163438, 2023). "Moreover, COVID-19 is associated with a cytokine storm, which is characterized by the overproduction of pro-inflammatory cytokines, such as interleukin-6 (IL-6) and tumor necrosis factor-alpha (TNF-α)." (PMID 38090596, 2023). "More importantly, IL-6 is a key marker of cellular aging, and the age-related strengthening of the IL-6 amplifier could be linked to COVID-19 mortality." (PMID 37124230, 2023). "ARDS is the leading cause of death due to COVID-19, characterized by high levels of pro-inflammatory cytokines (IL-6, IL-17, IL-1β, and TNF-α) and immune cell hyperactivation, a state called “cytokine storm” that may lead to multiorgan failure." (PMID 37368708, 2023). "Among them, interleukin-6 can predict COVID-19 severity, intubation risk, and mortality." (PMID 37158917, 2023). "Our major results point to an association of the IL6 C allele with COVID-19 severity." (PMID 37243282, 2023). "However, the brain inflammation associated with COVID-19 increases the concentration of cytokines that negatively affect adult human neurogenesis, e.g., IL-6, IL-1β, IL-1α, and TNF." (PMID 36672177, 2023). "Therefore, from the viewpoint of preventing aggravation in patients with severe COVID-19, revealing the mechanisms underlying excessively uncontrolled IL-6 production is important." (PMID 38030681, 2023). "For example, NF-κβ-mediated IL-6 synthesis in COVID-19 was speculated to be associated with the adversity of the disease." (PMID 37047115, 2023). "Among these cytokines, IL-6 seems to be particularly important, as very high levels of it have been associated with the severity of the disease, making it an attractive target in anti-COVID-19 therapy." (PMID 35744777, 2022). "GM-CSF and possibly IL-6 are secreted by the pathogenic IFN-ɣ+ GM-CSF+ T helper 1 cells to increase inflammatory CD14+CD16+ monocyte responses by increasing the concentration of IL-6 in COVID-19 patients." (PMID 35782361, 2022). "In support of our findings related to IL-6 and granzyme B as biomarkers of liver injury, a recent study demonstrated that IL-6 trans-signaling drives COVID-19-associated hepatic endotheliopathy, which is suggested as a possible mechanism underlying the liver injury." (PMID 35529862, 2022).